MUC1 (mucin 1, cell surface associated)
Diseases named in the same sentence as MUC1 in open-access papers (continued):
Sharing a sentence is not in itself a finding about the gene and the disease.
cancer (continued). "In contrast, GT-00AxIL15 targets a combined carbohydrate-protein epitope on MUC1 which is specifically expressed on a variety of carcinomas, their respective metastases as well as on cancer stem cells and is virtually absent on normal cells." (PMID 38338686, 2024). "Unfortunately, MUC-1 is overexpressed in many forms of carcinomas, where cancerous cells seize MUC-1 signal transduction pathways to boost their proliferation, invasiveness, and metastatic capacity." (PMID 39103402, 2024). "This cell line expresses endogenous MUC1, but to a lesser extent than carcinoma cells when cultured on CCP, but the expression is increased when cultured in Matrigel or on PCCM." (PMID 38289112, 2024). "Based on cancer cell specificity and its special roles in carcinogenesis, MUC1 is considered one of the most promising targets and biomarkers in cancer research." (PMID 37345016, 2023). "The DNPs are modified with MUC1 aptamers, which enable the recognition of the overexpressed MUC1 proteins located on the membrane of A549 human carcinoma epithelial cells for cancer targeting and biosensing." (PMID 36904404, 2023). "In epithelial malignancies such as PDAC, a dysregulation of the glycosylation pattern of normal MUC1 reveals novel cancer-specific epitopes (MUC1-CE)." (PMID 37578571, 2023). "This DNA-displaying nanoparticle encapsulates PTX and is conjugated with DNA aptamer, which specifically binds with Mucin-1 (MUC1) protein overexpressed by cancer cells." (PMID 36850121, 2023). "An increase in MUC1—EGFR interaction leads to the activation of this factor, which is likely associated with tumorigenesis and cancer progression." (PMID 37345016, 2023). "There were many reports demonstrating that interactions between Gal-3 with MUC1 via T antigen are able to induce various key steps in cancer progression and metastasis." (PMID 37685842, 2023). "As these cells enter carcinogenesis, MUC1 undergoes apical polarisation and exhibits an aberrant glycosylation pattern within the N-terminus which exposes cancer-specific epitopes within the variable number tandem repeat region (VNTR)." (PMID 37679594, 2023). "MUC1 is a transmembrane O-glycosylated glycoprotein that also plays an important role in cell adhesion by shielding the small CAMs and inhibiting cancer cell interaction with adjacent cells." (PMID 37444377, 2023). "MUC1 has always been considered a target for cancer therapy and diagnosis because it is upregulated and frequently aberrantly glycosylated in most adenocarcinomas." (PMID 37894512, 2023). "Cancer cells with poorer differentiation states also prevalently down-regulated MUC1 expression and immune-related pathways, and had poor infiltration of CD8+ T cells." (PMID 37347037, 2023). "When GFP-OMVs were added to HeLa cells stained with anti-MUC1 antibody, bright green fluorescence was detected in cells, demonstrating the OMVs’ ability to detect cancer cells." (PMID 37111538, 2023). "The relationships between MUC1 mucin with T antigen and galectin-3 seem to be very important in cancer development." (PMID 37345016, 2023). "The results exhibited that the MUC-1 aptamer can be used as a targeting moiety for MUC-1 positive cancer cells to achieve targeted drug delivery and better anticancer effect." (PMID 37149607, 2023). "MUC1 is involved in many functions of cancer cells, such as cell adhesion, proliferation, migration, invasion, and metabolic reprogramming." (PMID 36902242, 2023). "MUC1 is often overexpressed in cancer cells with its carbohydrate residues cleaved from the VNTR regions, enabling the immune system to access the peptide backbone." (PMID 38140114, 2023). "Cancer cells were treated with 40, 80, and 160 μM tiliroside, 5 μg/mL anti-MUC1, and flavonoid together with mAb." (PMID 37685842, 2023). "Previously, [177Lu]Lu-DOTA-C595 has been developed as a beta-emitting radioimmunoconjugate to target cancer-specific mucin 1 epitopes (MUC1-CE) overexpressed on PDAC." (PMID 37679594, 2023).
cancer (continued). "We present several case studies with varying stages of cancer development (I−III), mutation status (EGFR, ALK), and biomarker expression based on a three-gene panel (CD133, KRT19, and MUC1)." (PMID 36900350, 2023). "Previously, MUC1 and its autoantibodies detected in the serum of PCa patients have been utilized for early cancer detection." (PMID 36980526, 2023). "In most adenocarcinomas, mucin 1 (MUC1) is overexpressed, making it an attractive target for cancer biomarkers." (PMID 36741760, 2023). "MUC-1 overexpression can be used as a marker for cancer that suggests that the cancer is progressing." (PMID 37513835, 2023). "Suggested models of Gal-3—MUC1 interactions highlight the functional importance of the change of the cell surface glycosylation in cancer progression and metastasis." (PMID 37345016, 2023). "The interaction of MUC1 with lectins is enhanced when there is an abnormal increase in SLea and SLex on MUC1, which promotes the aggregation of cancer cells and their metastasis to distal sites." (PMID 37894512, 2023). "It is believed that interactions of Gal-3 with MUC1 via T antigen influence a number of key steps in cancer progression and metastasis." (PMID 37345016, 2023). "MUC1 appears to be a promising target in cancer cells because of its abundant and specifically altered expression and its differential distribution pattern compared to normal tissues." (PMID 37836581, 2023). "Although cancer-related MUC-1 is only available in full-length form in vivo, MUC-1-specific CD8+ T cells were found in patients with cancer." (PMID 38069400, 2023). "The immunohistochemical staining pattern of the anti-MUC1 monoclonal antibody, Ma695, was examined in cancer tissues, and subcellular localization was determined as apical, cytoplasmic or negative." (PMID 37002293, 2023). "Specifically, increased membrane expression of MUC1 is believed to correlate directly with cancer progression." (PMID 36707815, 2023). "Apart from that, incomplete O-glycan side chains leading to the production of underglycos1ylated forms of MUC1 reveal immunogenic epitopes which can generate the immune response and cancer-related inflammation." (PMID 37345016, 2023). "The expression of MUC1 is generally upregulated in most cancer cells, and the upregulated MUC1 is mainly in the plasma membrane and cytoplasm of cancer cells." (PMID 37894512, 2023). "MUC1 expression in the apical membrane is likely to represent a luminal A-like phenotype (low grade cancer resulting in the most favorable prognosis)." (PMID 37002293, 2023). "We have also demonstrated promising results considering the combined action of rosmarinic acid and anti-MUC1 monoclonal antibody in the same cancer cells." (PMID 37685842, 2023). "In cancer, Muc1 can form an extended hydrophilic interface on the surface of cell membranes that prevents cancer cell recognition by the immune cells and can also inhibit penetration of hydrophobic chemotherapeutics." (PMID 37174700, 2023). "MUC1 expression in cancer cells has been shown on both the apical border and the lateral cell membrane and in the cytoplasm (depolarized staining)." (PMID 36367122, 2023). "Previous studies have shown that the active subunit MUC1-CT is involved in tumorigenesis in lung and other cancers." (PMID 36810913, 2023). "An example includes the expression of a unique disaccharide carbohydrate, Sialy-Tn (STn), on the cell surface of cancer cells, including BC cells, which is connected to MUC-1." (PMID 37443570, 2023). "MUC1 vaccine formulations expose APCs to MUC1 with the goal of boosting antibody and T cell responses to cancer cells." (PMID 38140114, 2023). "Like other members of the family, TF antigen in MUC1 was also demonstrated to mediate GAL-4-driven adhesion of cancer cells to the endothelium." (PMID 37898403, 2023).
cancer (continued). "A previous study reported that a change in the CpG methylation status of MUC1 significantly alters its expression, leading to a pathological role of MUC1 in different cancers." (PMID 36980526, 2023). "MUC1 is also an oncogene and supports the maintenance of stemness in embryonic and cancer stem cells." (PMID 37529165, 2023). "Several studies have demonstrated that targeting MUC-1 was a successful option for the cancer vaccine because it is broadly dispersed in all tumors and cancers, including stem cell cancer." (PMID 37513835, 2023). "Intriguingly, MUC1 expressed on cancer cells has been reported to engage SIGLEC9 to modulate the TME." (PMID 36688997, 2023). "In particular, these studies indicate that both the VNTR (MUC1-N) and non-VNTR (MUC1-C) regions contribute to immune evasion by cancer cells, which needs to be taken into consideration and addressed during the further development of MUC1-based cancer vaccines." (PMID 37654484, 2023). "By means of the structural integration, a HOF electrochemical immunosensor was reported, which enabled the ultrasensitive detection of cancer biomarker, mucin-1 (MUC1)." (PMID 37339954, 2023). "MUC-1 expression analysis, RNA-seq analysis and drug response test were performed to demonstrate the superiority of this cancer model." (PMID 37434755, 2023). "[177Lu]Lu-DOTA-C595 is designed to target cancer-specific mucin 1 epitopes (MUC1-CE) overexpressed on most epithelial cancers, including PDAC." (PMID 37578571, 2023). "Apart from that, the glycosylation pattern of the extracellular domain of MUC1 in cancers differs distinctly from that of MUC1 expressed on healthy cells." (PMID 37345016, 2023). "Binding of galectin-3 to TF/MUC1 on cancer cells also increases cancer cell-cell homotypic aggregation and survival in the blood circulation." (PMID 37612278, 2023). "MUC1 overexpression enhances the invasion capacity of cancer cells by inhibiting E-cadherin-mediated cell-cell adhesion and integrin-mediated cell adhesion to extracellular matrix components." (PMID 36367122, 2023). "Expression of aberrant ST structures on MUC1 can promote cancer cell growth, and the immune system seems to play a role in this." (PMID 37894512, 2023). "Galectin-3 interacts with TF-antigen on the surface of the transmembrane mucin protein MUC-1 in cancer cells." (PMID 36873388, 2023). "This Tn+MUC1-CART therapy is currently undergoing in clinical Phase I study for the patients with Tn+MUC1 positive advanced cancers (NCT04025216)." (PMID 37509200, 2023). "Cancer-induced aberrant glycosylation produces the CA6 sialoglycotope of Mucin-1 (MUC1)-glycoprotein." (PMID 37569276, 2023). "MUC1, a glycoprotein present on the surfaces of epithelial cells, serves as a valuable biomarker for the early detection of cancers." (PMID 38137422, 2023). "It was revealed that cancer cells with gain and silencing of MUC1 indicated that MUC1 upregulates Gal-3 expression at the mRNA level." (PMID 37345016, 2023). "MUC1 mucin with T antigen and galectin-3 with high affinity to T disaccharide are both overexpressed in a variety of human cancers." (PMID 37345016, 2023). "MUC1 is a cell membrane glycoprotein that is overexpressed and/or abnormally glycosylated in more than 70% of cancers." (PMID 36902242, 2023). "Considering the presence of Mucin 1 (MUC1) as a heterodimeric protein with a remarkable rate of expression on cancer cells membrane, the potential of anti-MUC1 aptamer attracted a lot of attention for cancer therapy." (PMID 37009014, 2023). "Recently, MUC1 was rated by the American Cancer Institute Working Group as one of the most promising cancer vaccine-targeted antigens in clinical practice." (PMID 37894512, 2023). "When MUC1 is overexpressed in cancer along with the TF antigen, the smaller CAMs are exposed, which enhances the motility of the cancer cells and helps them migrate through the basement membrane." (PMID 37444377, 2023).
cancer (continued). "To support such ideas about the benefits of the potential application of anti-MUC1/tiliroside, we decided to also study some other factors involved in cancer development." (PMID 37685842, 2023). "The ability of tadalafil to enhance the efficacy of the mucin 1 (MUC1) cancer vaccine by inhibiting PDE5 in HNSCC patients is also under investigation (NCT02544880)." (PMID 36980527, 2023). "Cancer vaccines have been explored in BTCs using WT1 and MUC1 as antigens due to their ubiquity: WT1 is mutated in ~80% of BTCs, while MUC1 is overexpressed in ~90%." (PMID 37444422, 2023). "MUC1 expression in cancer cells has been shown on the apical border and the lateral cell membrane and in cytoplasm (depolarized staining)." (PMID 36367122, 2023). "Another domain consists of aptamers specifically targeting cancer cells, such as mucin 1 (MUC1), which exhibits unique and abundant expression on the surface of adenocarcinoma cells." (PMID 38107023, 2023). "Mucin-1 (MUC1) is a highly relevant antigen for cancer vaccination due to its overexpression and hypo-glycosylation in a high percentage of carcinomas." (PMID 38140114, 2023). "In cancers arising from ductal epithelium, MUC1 becomes overexpressed on the entire cell surface, and a less-glycosylated form of MUC1 is produced." (PMID 37869082, 2023). "In this review, we summarize current information about the interactions between the T antigen on MUC1 mucin and Gal-3, and their impact on cancer progression and metastasis." (PMID 37345016, 2023). "Glycoforms of MUC1 (MUC1 with different glycans) present in sera have long been used as serum markers for carcinomas and interstitial pneumonitis." (PMID 37002293, 2023). "One of the main features making MUC1 an attractive target for immunotherapies is that in cancer cells, MUC1 is hypoglycosylated, exposing the core epitopes of the extracellular domain that is normally masked by glycans." (PMID 35351156, 2022). "On a more general basis, cancer biomarkers can be found in a variety of isoforms: For example, MUC1 present in tumors (tMUC1 or TA-MUC1) has a different structure than normal MUC1." (PMID 36195928, 2022). "We found that the cancer subtype markers (GRP, CHGB, NEUROD1, and CHGA for NET; KRT5, DSC3, KRT6B, TP63, and KRT6A for SCC; and NKX2-1, KRT7, NAPSA, and MUC1 for ADC) were specifically expressed in the corresponding cancer subtypes." (PMID 35962452, 2022). "MUC1 is often upregulated and aberrantly glycosylated, making it a potential therapeutic target for cancer immunotherapy." (PMID 36612133, 2022). "As a result, CAR T-cells generated proinflammatory factors for eradicating the MUC1(+) cancer cells and grew after being stimulated by MUC1." (PMID 35883508, 2022). "Our previous work reported that MUC1 induces acquired chemotherapy resistance and stimulates cancer stem cell enrichment in cervical cancer." (PMID 36289190, 2022). "First, cancer cells that overexpressed MUC1 are resistant to the cytotoxicity of T and NK cells, according to in vitro studies." (PMID 35248049, 2022). "Cancer Cell Line Encyclopedia (CCLE) and Genomics of Drug Sensitivity in Cancer (GDSC) was used to analyze the relationship between MUC1 expression and drug sensitivity." (PMID 35879749, 2022). "Among the genetic loci identified in this study, rs4072037 (MUC1) and rs1053878 (ABO) have been reported to be associated with the occurrence and development of cancers." (PMID 35144566, 2022). "Altered glycosylation (and expression) of mucin 1 (MUC1) is one of the most studied PTM events and has been associated with several cancers." (PMID 36077528, 2022). "PCLS were embedded and we assessed the presence of metastatic cancer cells (Muc1+) and proliferating cells (Ki67+)." (PMID 35022267, 2022).
cancer (continued). "In cancer cells, MUC1 promotes cell growth, migration and invasion, and it is involved in metastatic progression." (PMID 36430448, 2022). "We further verified the cancer promotion function of pivotal genes HILPDA and MUC1 and revealed the probable association between them and ferroptosis." (PMID 36439512, 2022). "Tecemotide is an active immunotherapeutic agent targeting a cell surface glycoprotein, mucin 1 (MUC1), and is highly expressed in various malignant tumors and is associated with cellular growth, invasion, and metastasis." (PMID 36341464, 2022). "In this study, we used gene expression data obtained from the the Cancer Genome Atlas (TCGA) and the Gene Expression Omnibus (GEO) database to explore the expression of MUC1 in human BC samples." (PMID 35879749, 2022). "Such glycoforms can be present at cell surfaces as well as on glycoproteins (such as MUC1) released to extracellular matrix; they can be aberrantly overexpressed during cancer development in both localizations." (PMID 35955735, 2022). "According to this, we postulate the polyphenolic compounds applied in the study can act as potential anti-cancer agents because of inhibitory effects on MUC1 oncoprotein." (PMID 35955735, 2022). "Our previous paper and other papers revealed that MUC1 confers resistance to anticancer agents in various cancers and represents be an important target for cancer therapy." (PMID 36289190, 2022). "Overexpression of MUC1 provided additional advantages in different biological processes such as cell proliferation, cancer cell migration and resistance to chemotherapy." (PMID 36430448, 2022). "Two different CAR MUC1 constructs were transduced into primary T cells and evaluated their characteristics and antitumor activities against MUC1+ cancer cells." (PMID 36457849, 2022). "So far, many anti-MUC1 antibodies have been developed, and some of them are specific to cancer progression." (PMID 35887202, 2022). "We focused on antibodies to MUC1, an oncoprotein that is differentially glycosylated in cancer cells and is overexpressed in >90% of all EOC." (PMID 36428740, 2022). "MUC1 belongs to the mucin family, playing the oncogenic/mitogenic roles in cancer cells and interacting with several other oncogenic receptors and pathways, such as HER2, β-catenin, NF-κB, and estrogen receptor (ERα)." (PMID 35248049, 2022). "The IC50 values (the concentration at which the nanobody exerted half of its maximal inhibitory effect) of the anti‐MUC1 nanobody against MUC1‐positive human cancer cell lines ranged from 1.2 to 14.3 nm." (PMID 34694686, 2022). "The top 30 genes that were found to be differentially expressed in low vs high MUC1 tumors have significant roles in inflammation, cancer progression and OS." (PMID 35237602, 2022). "Thus, MUC1 may activate and mediate intracellular signaling by associating with various protein receptors and modulating their functions leading to altered signaling in cancer cells." (PMID 35955735, 2022). "Our risk model can predict OS survival outcomes, and we propose that HILPDA and MUC1 are potential targets for cancer therapy." (PMID 36439512, 2022). "Here, our research highlighted that in cancer cells with high level of MUC1, the referenced dosage and actual cytotoxicity of clinical drugs need to be modulated according to the level of MUC1 O-glycosylation, especially in BRCA and PAAD." (PMID 35970845, 2022). "Vaccination strategies appear to be of particular interest, as MUC1 is overexpressed in BC and other cancer histologies and has been reported to have a high level of immunogenicity." (PMID 35406491, 2022). "Another cancer vaccine in clinical trial is based on MUC1 bearing Tn antigens (Tn-MUC1) pulsed with autologous DCs." (PMID 36291752, 2022).